PTK2 (protein tyrosine kinase 2)
Description:
Non-receptor protein-tyrosine kinase that plays an essential role in regulating cell migration, adhesion, spreading, reorganization of the actin cytoskeleton, formation and disassembly of focal adhesions and cell protrusions, cell cycle progression, cell proliferation and apoptosis. Required for early embryonic development and placenta development. Required for embryonic angiogenesis, normal cardiomyocyte migration and proliferation, and normal heart development. Regulates axon growth and neuronal cell migration, axon branching and synapse formation; required for normal development of the nervous system. Plays a role in osteogenesis and differentiation of osteoblasts. Functions in integrin signal transduction, but also in signaling downstream of numerous growth factor receptors, G protein-coupled receptors (GPCR), EPHA2, netrin receptors and LDL receptors. Forms multisubunit signaling complexes with SRC and SRC family members upon activation; this leads to the phosphorylation of additional tyrosine residues, creating binding sites for scaffold proteins, effectors and substrates. Regulates numerous signaling pathways. Promotes activation of phosphatidylinositol 3-kinase and the AKT1 signaling cascade. Promotes activation of MAPK1/ERK2, MAPK3/ERK1 and the MAP kinase signaling cascade. Promotes localized and transient activation of guanine nucleotide exchange factors (GEFs) and GTPase-activating proteins (GAPs), and thereby modulates the activity of Rho family GTPases. Signaling via CAS family members mediates activation of RAC1. Phosphorylates NEDD9 following integrin stimulation. Phosphorylates SRC; this increases SRC kinase activity. Phosphorylates ACTN1, ARHGEF7, GRB7, RET and WASL. Promotes phosphorylation of PXN and STAT1; most likely PXN and STAT1 are phosphorylated by a SRC family kinase that is recruited to autophosphorylated PTK2/FAK1, rather than by PTK2/FAK1 itself. Promotes phosphorylation of BCAR1; GIT2 and SHC1; this requires both SRC and PTK2/FAK1. Promotes phosphorylation of BMX and PIK3R1. Isoform 6 (FRNK) does not contain a kinase domain and inhibits PTK2/FAK1 phosphorylation and signaling. Its enhanced expression can attenuate the nuclear accumulation of LPXN and limit its ability to enhance serum response factor (SRF)-dependent gene transcription. [Isoform 6]: Isoform 6 (FRNK) does not contain a kinase domain and inhibits PTK2/FAK1 phosphorylation and signaling. Its enhanced expression can attenuate the nuclear accumulation of LPXN and limit its ability to enhance serum response factor (SRF)-dependent gene transcription.
Synonyms: FADK 1; FRNK; PPP1R71; FAK; FAK1; FADK; p125FAK; pp125FAK
Tractability: Small molecule: a drug acting on it is in phase 2 or 3 trials; a structure with a bound ligand is known; a high-quality ligand is known; it has a high-quality binding pocket; it belongs to a druggable protein family. Antibody: UniProt places it where antibodies can reach, with medium confidence; its Gene Ontology location is reachable by antibodies, with medium confidence. PROTAC: it is named in the literature on targeted protein degradation; UniProt records ubiquitination sites on it; ubiquitination databases record sites on it; its protein half-life has been measured; a small molecule that binds it is known.
Target class: Enzyme; TK protein kinase group; Tyrosine protein kinase Fak family; Kinase; Protein Kinase
Chemical probes: BI-0319 (high quality), BI-3663 (high quality), BJG-03-025 (high quality), DEFACTINIB (high quality), PROTAC FAK degrader 1 (high quality)
Safety:
Unwanted effects reported when the protein is acted on. In parentheses: how it was acted on, where the effect was seen, and who reports it.
abnormal platelet production and function (activation; source: Brennan et al. (2024))
cardiac hypertrophy (inhibition; cardiovascular; source: Brennan et al. (2024))
Hypertension (inhibition; cardiovascular; source: Brennan et al. (2024))
liver fibrosis (activation; liver; source: Brennan et al. (2024))
metabolism disorder (inhibition; metabolic; source: Brennan et al. (2024))
platelet overproduction (inhibition; source: Brennan et al. (2024))
QT prolongation (inhibition; cardiovascular; source: Brennan et al. (2024))
reduced platelet adhesion (inhibition; source: Brennan et al. (2024))
reduced platelet aggregation (inhibition; source: Brennan et al. (2024))
skin fibrosis (activation; skin; source: Brennan et al. (2024))
Tumour promotion: increased metabolism and increased cell migration/invasion (activation; source: Brennan et al. (2024))
cardiac arrhythmia (cardiovascular system; source: Lamore et al. (2017))
heart disease (cardiovascular system; source: Force et al. (2011))
Gene: Protein-coding gene on chromosome 8 (140,657,900 to 141,002,216, reverse strand). Ensembl gene ENSG00000169398.
Subcellular location: Cell junction, focal adhesion; Cell membrane; Cytoplasm, perinuclear region; Cytoplasm, cell cortex; Cytoplasm, cytoskeleton; Cytoplasm, cytoskeleton, microtubule organizing center, centrosome; Nucleus; Cytoplasm, cytoskeleton, cilium basal body; Cytoplasm
Subcellular location (Human Protein Atlas): Focal adhesion sites; Cytosol; Primary cilium; Primary cilium tip; Vesicles
Pathways (Reactome):
Signal Transduction: Estrogen-dependent nuclear events downstream of ESR-membrane signaling; Extra-nuclear estrogen signaling; GRB2:SOS provides linkage to MAPK signaling for Integrins; Integrin signaling; MET activates PTK2 signaling; RAF/MAP kinase cascade; RHO GTPases Activate WASPs and WAVEs; VEGFA-VEGFR2 Pathway; p130Cas linkage to MAPK signaling for integrins
Developmental Biology: DCC mediated attractive signaling; EPHB-mediated forward signaling; NCAM signaling for neurite out-growth
Cell-Cell communication: Signal regulatory protein family interactions
Cellular responses to stimuli: Turbulent (oscillatory, disturbed) flow shear stress activates signaling by PIEZO1 and integrins in endothelial cells
Disease: FCGR3A-mediated phagocytosis
Immune System: Regulation of actin dynamics for phagocytic cup formation
Programmed Cell Death: Apoptotic cleavage of cellular proteins
Gene Ontology:
Molecular function: actin binding; integrin binding; JUN kinase binding; molecular function activator activity; non-membrane spanning protein tyrosine kinase activity; protein binding; protein kinase binding; protein phosphatase binding; protein tyrosine kinase activity; protein tyrosine phosphatase activity; SH2 domain binding; ATP binding; protein kinase activity
Biological process: cell migration; ephrin receptor signaling pathway; growth hormone receptor signaling pathway; integrin-mediated signaling pathway; negative regulation of anoikis; negative regulation of apoptotic process; negative regulation of cell adhesion mediated by integrin; negative regulation of cell-cell adhesion; positive regulation of cell migration; positive regulation of cell-cell adhesion mediated by integrin; positive regulation of epithelial cell migration; positive regulation of epithelial to mesenchymal transition; positive regulation of fibroblast migration; positive regulation of macrophage chemotaxis; positive regulation of macrophage proliferation; positive regulation of phosphatidylinositol 3-kinase/protein kinase B signal transduction; positive regulation of wound healing; regulation of cell population proliferation; regulation of cell shape; regulation of epithelial cell migration; regulation of focal adhesion assembly; regulation of osteoblast differentiation; regulation of substrate adhesion-dependent cell spreading; transforming growth factor beta receptor signaling pathway; angiogenesis; and 22 more
Cellular component: ciliary basal body; cytoplasm; cytosol; focal adhesion; nucleus; stress fiber; cytoskeleton; plasma membrane; cell cortex; centrosome; perinuclear region of cytoplasm
Genetic constraint (gnomAD): Loss-of-function variants: 35 observed, 116.24 expected, observed/expected ratio (o/e) 0.3, 90% interval 0.23 to 0.4. The upper end of that interval is the gene's LOEUF score, 0.4, which puts it in group 1 of 6, group 1 being the genes least tolerant of losing a copy. Missense variants: 797 observed, 1,148.4 expected, observed/expected ratio (o/e) 0.69, 90% interval 0.65 to 0.74. Synonymous variants: 379 observed, 407.82 expected, observed/expected ratio (o/e) 0.93, 90% interval 0.85 to 1.01.
Homologues: Orthologues: macaque PTK2 (99% identical), mouse Ptk2 (97% identical), rat Ptk2 (97% identical), guinea pig PTK2 (96% identical), dog PTK2 (93% identical), pig PTK2 (93% identical), chimpanzee PTK2 (92% identical), rabbit PTK2 (91% identical), tropical clawed frog ptk2 (89% identical), zebrafish ptk2ab (79% identical), zebrafish ptk2aa (59% identical). Paralogues in human: PTK2B (43% identical), ABL1 (19% identical), ABL2 (18% identical), TNK2 (17% identical), SRC (15% identical), TYK2 (15% identical), FYN (15% identical), JAK1 (15% identical), LYN (15% identical), SYK (15% identical), ZAP70 (15% identical), BLK (15% identical), and 20 more.
Diseases named in the same sentence as PTK2 in open-access papers:
PTK2 is named in the same sentence as 375 diseases in open-access papers, as found by Europe PMC text mining. Sharing a sentence is not in itself a finding about the gene and the disease. The quoted sentences say what the papers report.
breast carcinoma (439 papers, 2005 to 2026). "Overexpression of EPHA10, LYN, and PTK2 (BL1 subtype-specific TK genes) is linked to the severity of breast cancer and can be used as the biomarker for TNBC." (PMID 36672350, 2023). "In our study, these ARGs were all statistically significant in gene expression between breast cancer and normal tissues, and all had amplification mutations in BC, with PTK2 and RECQL4 being the most prominent." (PMID 36323529, 2023). "The UALCAN online tool was used to analyze the association of PTK2 mRNA expression with clinicopathological parameters, including nodal metastasis status, breast cancer subclasses, age, sex, race, and menopausal status." (PMID 36533074, 2022). "Among 12 CpG sites of PTK2, cg11398680, cg11559446, cg23913941, and cg24143495 were associated with poor prognosis in breast cancer patients." (PMID 36533074, 2022). "In this study, we used various public databases to explore the differential expression of PTK2 in breast cancer tissues and normal tissues, its diagnostic value in breast cancer, and its correlation with clinicopathological parameters." (PMID 36533074, 2022). "However, copy number gains of PTK2, the gene encoding FAK, has been shown to be a predictive marker for sensitivity to FAK inhibition in a breast cancer cell line, and PTK2 gene amplifications confer worse prognosis in patients with various cancer types." (PMID 41019359, 2025). "Also, PTK2, the gene that encodes Fak, is highly amplified in human breast cancer and is associated with metastasis-free survival." (PMID 39123481, 2024). "In addition, we assessed the association of PTK2 gene alterations with the survival of breast cancer patients." (PMID 36533074, 2022). "To establish potential associations corresponding to the expression of FAK in human breast cancers, we queried the METABRIC dataset that includes a large patient cohort (2509 tumors) through cBioPortal and found that FAK gene (Official Symbol: PTK2) was amplified in 415 (21%) of these tumors." (PMID 32493400, 2020). "By analyzing the expression data of 3554 breast tumor samples collected by an online Kaplan-Meier survival analysis tool, we found that higher expression of SMARCE1 or PTK2 is associated with shorter interval of relapse-free survival (RFS) of breast cancer patients." (PMID 27495308, 2016). "In addition, to better understand whether PTK2 could affect the progression of breast cancer, we explored the association between PTK2 and clinicopathological characteristics in breast cancer." (PMID 36533074, 2022). "CircRPAP2 interacts with SRSF1, hindering its splicing regulation of PTK2 precursor mRNAs, leading to decreased PTK2 protein levels and subsequently inhibiting breast cancer cell migration and invasion." (PMID 40740236, 2025). "For instance, circRPAP2 can bind to the oncogenic splicing factor SRSF1 to compete with the binding between SRSF1 and PTK2 pre-mRNA, thereby attenuating SRSF1-mediated alternate splicing of PTK2 and reduce its expression in breast cancer." (PMID 39550559, 2024). "RET has previously been shown to activate cytoskeletal remodeling and migration by binding and phosphorylating FAK (PTK2) and has been reported to activate similar mechanisms in breast cancer models." (PMID 36918928, 2023). "Upregulation of PTK2 is correlated with poor survival and drug resistance in patients with breast cancer." (PMID 35290401, 2022). "In conclusion, our study highlighted the value of PTK2 as a potential novel prognostic biomarker for breast cancer." (PMID 36533074, 2022).
breast carcinoma (continued). "According to the Kaplan‒Meier survival curves, breast cancer patients with high PTK2 expression exhibited poor overall survival (OS), but disease-specific survival (DSS) and progression-free interval (PFI) were not affected." (PMID 36533074, 2022). "In this study, we explored the prognostic value and biological functions of PTK2 in breast cancer using various public databases." (PMID 36533074, 2022). "Among these patients, PTK2 gene alterations were mainly amplified in breast cancer, invasive breast cancer, and metastatic breast cancer." (PMID 36533074, 2022). "In this study, we used bioinformatics analysis of the TIMER, UALCAN, and TCGA public databases and found that PTK2 expression levels in breast cancer tissues were higher than those in normal breast tissues." (PMID 36533074, 2022). "In particular, homologs AKT1, AKT2, ERBB2, FGFR2, and PIK3CA in CGC play important roles in breast cancer progression, mediating breast cancer risk, corresponding to the driver candidates RPS6KA1, SGK1, PTK2, IGF1R, PIK3CB, and PRKDC predicted by DriverMP." (PMID 38091511, 2022). "To understand the biological significance of PTK2 in breast cancer, we analyzed the positively and negatively correlated co-expressed genes of PTK2 in breast cancer utilizing the LinkedOmics database." (PMID 36533074, 2022). "Next, Kaplan–Meier survival curves and PrognoScan analysis showed that PTK2 was highly expressed in breast cancer and was related to poor prognosis." (PMID 36533074, 2022). "The DNA methylation of PTK2 in breast cancer tissues was higher than that in normal tissues, and high PTK2 methylation was correlated with poor prognosis in breast cancer patients." (PMID 36533074, 2022). "PTK2 mRNA expression was significantly elevated in breast cancer patients compared with that in healthy individuals." (PMID 36533074, 2022). "PTK2 mRNA expression was significantly elevated in breast cancer tissues compared with that in adjacent normal tissues." (PMID 36533074, 2022). "In terms of tumor histology, PTK2 mRNA expression was higher in patients with breast cancer classified as LDC, ILC, mixed, other, and medullary than the expression in other classification categories." (PMID 36533074, 2022). "Our study provides novel insights that show the potential role of PTK2 in breast cancer and its potential role as a prognostic biomarker." (PMID 36533074, 2022). "By integrating multiple datasets, we found that PTK2 mRNA expression in breast cancer tissue was higher than that in normal breast tissue or adjacent tissue." (PMID 36533074, 2022). "With increasing evidence that the lncRNA–miRNA–mRNA ceRNA network plays a critical role in multiple human cancers, we sought to analyze and construct a breast cancer ceRNA network involving PTK2." (PMID 36533074, 2022). "We first examined PTK2 expression in breast cancer cell lines (MCF-7, BT-549, and MDA-MB-231) and the normal human mammary epithelial cell line, MCF-10A." (PMID 36533074, 2022). "Next, we performed in vitro experiments to explore the effects of PTK2 on the biological behavior of breast cancer." (PMID 36533074, 2022). "Overexpression of PTK2 has been described in a diverse assortment of human tumors, including breast cancer, hepatocellular carcinoma, and head and neck cell carcinoma." (PMID 36533074, 2022). "Analysis of the TIMER database found that PTK2 was highly expressed in 13 cancers, and the expression of PTK2 in breast cancer samples was significantly increased." (PMID 36533074, 2022). "Other investigations have revealed that high PTK2 levels are associated with a short relapse-free survival (RFS) and tumor relapse in breast cancer." (PMID 33562737, 2021). "In this regard, we ascertained that the PTK2 high group has a significant poorer overall survival respect to the PTK2 low group in all types of breast cancer as well as in TNBC." (PMID 30728047, 2019).